CBLC (Cbl proto-oncogene C)
Description:
Acts as an E3 ubiquitin-protein ligase, which accepts ubiquitin from specific E2 ubiquitin-conjugating enzymes, and then transfers it to substrates promoting their degradation by the proteasome. Functionally coupled with the E2 ubiquitin-protein ligases UB2D1, UB2D2 and UB2D3. Regulator of EGFR mediated signal transduction; upon EGF activation, ubiquitinates EGFR. Isoform 1, but not isoform 2, inhibits EGF stimulated MAPK1 activation. Promotes ubiquitination of SRC phosphorylated at 'Tyr-419'. In collaboration with CD2AP may act as regulatory checkpoint for Ret signaling by modulating the rate of RET degradation after ligand activation; CD2AP converts it from an inhibitor to a promoter of RET degradation; the function limits the potency of GDNF on neuronal survival.
Synonyms: RNF57; CBL-3; CBL-SL
Tractability: Antibody: its Gene Ontology location is reachable by antibodies, with medium confidence. PROTAC: UniProt records ubiquitination sites on it; ubiquitination databases record sites on it.
Target class: Enzyme; Transferase
Gene: Protein-coding gene on chromosome 19 (44,777,845 to 44,802,291, forward strand). Ensembl gene ENSG00000142273.
Subcellular location (Human Protein Atlas): Nucleoplasm; Aggresome
Gene Ontology:
Molecular function: epidermal growth factor receptor binding; phosphotyrosine residue binding; protein binding; SH3 domain binding; ubiquitin protein ligase activity; receptor tyrosine kinase binding; zinc ion binding; calcium ion binding; ubiquitin-protein transferase activity
Biological process: negative regulation of epidermal growth factor receptor signaling pathway; negative regulation of MAPK cascade; protein ubiquitination; ubiquitin-dependent protein catabolic process; signal transduction; cell surface receptor signaling pathway; protein catabolic process; regulation of signaling
Cellular component: membrane raft; plasma membrane
Genetic constraint (gnomAD): Loss-of-function variants: 45 observed, 54.56 expected, observed/expected ratio (o/e) 0.82, 90% interval 0.65 to 1.06. The upper end of that interval is the gene's LOEUF score, 1.06, which puts it in group 4 of 6, group 1 being the genes least tolerant of losing a copy. Missense variants: 629 observed, 567.15 expected, observed/expected ratio (o/e) 1.11, 90% interval 1.04 to 1.18. Synonymous variants: 254 observed, 230.05 expected, observed/expected ratio (o/e) 1.1, 90% interval 1 to 1.23.
Homologues: Orthologues: chimpanzee CBLC (99% identical), macaque CBLC (93% identical), pig CBLC (78% identical), dog CBLC (76% identical), rat Cblc (72% identical), mouse Cblc (71% identical), guinea pig CBLC (70% identical), Drosophila melanogaster Cbl (41% identical), Caenorhabditis elegans sli-1 (39% identical). Paralogues in human: CBL (46% identical), CBLB (46% identical).
Diseases named in the same sentence as CBLC in open-access papers:
CBLC is named in the same sentence as 89 diseases in open-access papers, as found by Europe PMC text mining. Sharing a sentence is not in itself a finding about the gene and the disease. The quoted sentences say what the papers report.
homocystinuria (26 papers, 2010 to 2025). An autosomal recessive inherited metabolic disorder caused by mutations in the CBS, MTHFR, MTR, and MTRR genes. "In the present study, we have described the clinical course, biochemical features, genetic findings, and the outcomes of 56 late-onset patients with combined MMA and homocystinuria caused by cblC deficiency." (PMID 36056359, 2022). "In fact, an epigenetic cause of IEMs, named epi-cblC, has been recently reported for methylmalonic aciduria and homocystinuria, cobalamin C type (cblC disease; OMIM #277400)." (PMID 34215320, 2021). "first mapped the cblC locus and identified mutations in the MethylMalonic Aciduria (Cobalamin deficiency) cblC type, with Homocystinuria (MMACHC gene, OMIM*609831)." (PMID 31470807, 2019). "Based on the patients’ biochemical features, MMA can be classified as isolated MMA or combined methylmalonic aciduria and homocystinuria, and the latter consists of five subtypes, including cblC, cblD, cblF, cblJ and cblX deficiencies." (PMID 30157807, 2018). "Other forms of “atypical” HUS (aHUS) are caused by abnormalities in the cblC pathway (methylmalonic aciduria and homocystinuria, cblC complementation type [MMACHC])." (PMID 28884355, 2018). "The cblC, cblD, and cblF defects cause homocystinuria in addition to MMA as both AdoCbl and methylcobalamin syntheses are disturbed." (PMID 25738478, 2015). "The mut, cblA, cblB, and cblH types show only MMA and are therefore called isolated MMA; cblC, cblD, and cblF deficiencies are usually associated with homocystinuria, and the resulting condition is called combined methylmalonic aciduria and homocystinuria (MMA-HC)." (PMID 36777632, 2023). "In summary, an early-onset methylmalonic aciduria and homocystinuria, cblC type was evidenced through metabolic investigations of a neurological impairment associated with failure to thrive." (PMID 39916850, 2025). "Methylmalonic aciduria and homocystinuria CblC, CblD-Combined, CblF and CblJ types are mainly responsive to intramuscular OHcbl administration." (PMID 39916850, 2025). "This case-report describes an early-onset methylmalonic aciduria and homocystinuria, cblC type presentation through neurological manifestations and failure to thrive." (PMID 39916850, 2025). "Methylmalonic aciduria and homocystinuria, cobalamin C type (cblC), constitute the most common inborn error of intracellular cobalamin metabolism." (PMID 39916850, 2025). "The diagnosis of methylmalonic aciduria and homocystinuria, CblC type was confirmed on a next generation sequencing panel of 216 genes responsible for metabolic defects and hepatic insufficiencies." (PMID 39916850, 2025). "Combined methylmalonic acidemia and homocystinuria, cblC type is an inborn error of intracellular cobalamin metabolism and the most common one." (PMID 38245797, 2024). "Cobalamin C (cblC) defects, also called combined methylmalonic aciduria and homocystinuria cblC type, are the most common inherited disorders of cobalamin metabolism, with an incidence of approximately 1/100,000 live births." (PMID 36590295, 2022). "Combined methylmalonic academia and homocystinuria, cobalamin C type (cblC defect) is the most frequent genetic disorder of cobalamin metabolism." (PMID 33691766, 2021). "Combined methylmalonic acidemia and homocystinuria, cobalamin C type (cblC defect) is the most common inborn error of cobalamin metabolism, and different approaches have been applied to its prenatal diagnosis." (PMID 33691766, 2021). "An epigenetic cause of IEMs has been recently described for the autosomal recessive methylmalonic aciduria and homocystinuria, cblC type (cblC disease), and it has been named epi-cblC." (PMID 34215320, 2021). "Based on this premise, the severity of clinical presentations of inborn errors of metabolism, such as classical homocystinuria or the cobalamin C (cblC) defect, affecting this pathway is unsurprising." (PMID 33179601, 2020).
homocystinuria (continued). "The most common disorder of intracellular vitamin B12 metabolism is methylmalonic aciduria and homocystinuria, cblC complementation type (MMACHC; phenotype MIM# 277400), which accounts for ~80 % of all cases." (PMID 27289364, 2017). "Methylmalonic aciduria and homocystinuria, cobalamin C (cblC) type, is the most common genetic type of functional cobalamin (vitamin B12) deficiency." (PMID 27289364, 2017). "Methylmalonic aciduria and homocystinuria, cblC type, is the most common inborn error of cellular vitamin B12 metabolism." (PMID 20219402, 2010). "Variations in MMACHC have been detected as MMA and homocystinuria, cblC type." (PMID 34733806, 2021). "Finally, methylmalonic acidemia (MMA) and homocystinuria, cblC type, were diagnosed based on genetic findings." (PMID 34733806, 2021). "At the age of 34, when her first pregnancy resulted in an intrauterine death of a morphologically normal growth-restricted foetus, she was diagnosed with homocystinuria and methylmalonic aciduria due to cyanocobalamin C (cblC) defect, which was confirmed by molecular investigation." (PMID 31470807, 2019). "In mainland China, cblC defects are the main type of combined methylmalonic aciduria (MMA) and homocystinuria." (PMID 36590295, 2022). "The cblC type chosen in this study accounted for 94.7% of Chinese MMA combined with homocystinuria but not for the other four subtypes of the combined cobalamin metabolism (cblD, cblF, cblJ, and cblX) in our current assay." (PMID 35069678, 2021).
homocysteinemia (14 papers, 2017 to 2025). "In patients with MMA and homocysteinemia, methionine synthase activity is reduced due to deficiency of the cofactor CblC, resulting in significantly elevated homocysteine levels in utero." (PMID 40830795, 2025). "Consistent with most literature reports, the cblC type is the most common methylmalonic acid associated with homocysteinemia." (PMID 38355526, 2024). "Macrocytic anemia and hyperhomocysteinemia are useful clues for patients with hematuria and proteinuria caused by cblC defect." (PMID 36704130, 2022). "Peripheral neuropathy remains a classical but underdiagnosed complication of cblC defect, especially in late-onset cblC disease caused by mutations in the methylmalonic aciduria type C and homocysteinemia (MMACHC) gene." (PMID 33324334, 2020). "Combined methylmalonic acidemia (MMA) and homocysteinemia are a group of autosomal recessive disorders caused by inborn errors of cobalamin metabolism, including CblC, D, F, and J, with cblC being the most common subtype." (PMID 28327205, 2017). "Homocysteinemia associated with MMA includes cblC, cblD, cblF, cblJ, and cblX types." (PMID 38355526, 2024). "Betaine has been used for more than 30 years in pyridoxine non-responsive cystathionine beta-synthase (pnrCBS) and cobalamin C (cblC) deficiencies to lower the hyperhomocysteinemia, although little is known about the optimal therapeutic dosage and its pharmacokinetic in these patients." (PMID 36376887, 2022). "Patients with cblC, cblD, and cblF defects are classified as having MMA combined with homocysteinemia accounting for 60–80% of cases in China, and cblC defects are the most common subtype." (PMID 36590295, 2022). "Among the seven patients who were diagnosed with MMA and homocysteinemia, homozygotic or compound heterozygous MMACHC mutations were found in four of them, which suggested type CblC." (PMID 31969166, 2020). "Hyperhomocysteinemia should be differentiated from cblC-MMA, which possesses some similar biochemical characteristics with cblC-MMA." (PMID 36582607, 2022).
methylmalonic acidemia (13 papers, 2017 to 2025). A genetically heterogenous inherited disorder characterized by abnormalities in the metabolism of lipids and proteins. "cblC deficiency is the most common type of methylmalonic acidemia in China, which can be prevented and treated." (PMID 40841656, 2025). "In a study involving patients with cblC deficient methylmalonic acidemia and hydrocephalus, characterized by high blood propionylcarnitine, it was observed that 61.8% of patients had epilepsy, and treatment with l‐carnitine resulted in symptom improvement." (PMID 38898641, 2024). "Possibly, additional biochemical abnormalities such as methylmalonic acidemia and/or methionine deficiency—as in cblC defect (this study) or in methylenetetrahydrofolate dehydrogenase 1 (MTHFD1) deficiency (OMIM 172460,)—are required to develop TMA." (PMID 27289364, 2017). "In evaluating propionylcarnitine (C3), the mean concentration was similar amongst newborns with propionic acidemia (PA), methylmalonic acidemia, and all false positive cases, while newborns with cobalamin C (cblC) deficiency had an overall higher mean C3 concentration." (PMID 35225935, 2022). "cblC defect is the most common type of methylmalonic acidemia in China." (PMID 37770946, 2023). "Cobalamin C defect (cblC, OMIM 277,400), accounting for 70% of cases with methylmalonic acidemia (MMA), is the most common disorder of organic acid metabolism in China." (PMID 37770946, 2023).
cobalamin deficiency (11 papers, 2014 to 2022). "The difference in the redox behavior of different forms of vitamin B12 may underlie their different efficacy in treating cobalamin deficiency caused by defects in cblC." (PMID 36232333, 2022). "Indeed, our results for tHcy and MMA levels provided additional useful information in the screening of cblC, cobalamin deficiency, MTHFRD, and CBSD." (PMID 34287228, 2021). "However, while biochemical markers (homocysteine, MMA, C3, and methionine) normalize in patients with nutritional vitamin B12 deficiency following initiation of cobalamin supplementation, they improve, but often remain abnormal in patients with cblC." (PMID 32905057, 2020). "The complementation groups cblC, cblD and cblX are caused by mutations in the MMACHC (methylmalonic aciduria (cobalamin deficiency) cblC type, cblC), MMADHC (methylmalonic aciduria (cobalamin deficiency) cblD type, cblD) and the HCFC1 (host cell factor C1, cblX) genes." (PMID 27061115, 2016). "However it has been shown that demyelination in the cblC defect (and most probable also in acquired vitamin B12 deficiency) seems associated with low levels of S-adenosylmethionine resulting from the impaired remethylation of Hcy to Met." (PMID 25398587, 2014).
Methylmalonic aciduria (11 papers, 2016 to 2025). Increased concentration of methylmalonic acid in the urine. "It is worth noting that genetic testing for methylmalonic acidurias must consider epi-cblC, and pathogenic variants must be searched for in MMACHC and PRDX1." (PMID 40565527, 2025). "cblC deficiency is the most common type of methylmalonic aciduria in China." (PMID 36056359, 2022). "Anti-B12 molecules have been synthesized with an “upper” axial substituent, that is inert to the Cbl-reducing enzyme methylmalonic aciduria and homocystinuria type C protein (CblC)." (PMID 28910388, 2017).
breast carcinoma (7 papers, 2013 to 2024). "We validated this observation by demonstrating that silencing of CBLC causes increased sensitivity to olaparib in breast cancer cell line models and that defective homologous recombination (HR) DNA repair is the likely cause." (PMID 25883215, 2015). "The four TSGs: CBLC, CDH11, LZTR1, and TET2 previously shown to be most frequently mutated in 1KGP were also observed to display changes in ASE in breast cancer." (PMID 32064050, 2020). "We also assessed the effect on progression of the MCF7 breast cancer cells through the cell cycle in response to CBLC silencing." (PMID 25883215, 2015).
lung adenocarcinoma (7 papers, 2021 to 2025). A carcinoma that arises from the lung and is characterized by the presence of malignant glandular epithelial cells. "According to the immune staining intensity comparisons provided by the HPA database, the expression levels of FABP4, GDF10, and LTBP4 were higher in normal samples, while the expression level of CBLC was higher in lung adenocarcinoma samples." (PMID 40766337, 2025). "And similar to our discovery that CBLC is upregulated in prostate tumors, CBLC has been shown to be overexpressed in lung adenocarcinomas, furthering the notion that CBLC is capable of promoting tumorigenesis." (PMID 38045004, 2023). "There is evidence that E3 ubiquitin ligase CBLC positively regulated the stability of AURKA via ubiquitination in lung adenocarcinoma." (PMID 36973424, 2023). "The expression of CBLC is higher in different tumor types including lung, pancreatic, breast, and colorectal cancer cells and has been suggested as a therapeutic target in lung adenocarcinoma." (PMID 35765648, 2022). "The analysis results revealed, the high expression of CBLC in LUAD is positively correlated with poor clinical and pathological stages in patients, which means that the high expression of CBLC may be an indicator of poor progression and prognosis of lung adenocarcinoma." (PMID 40766337, 2025). "Cbl Proto-Oncogene C (CBLC) was demonstrated to enhance epidermal growth factor receptor dysregulation and signaling in lung adenocarcinoma." (PMID 34722520, 2021). "Finally, SFTPA1, PLXNB3, BIRC5, CBLC, and ACVRL1 were screened out based on the intersection between the top 10 differentially expressed genes in lung adenocarcinoma (LUAD) and lung squamous cell carcinoma (LUSC)." (PMID 34181042, 2022).
lung carcinoma (5 papers, 2021 to 2025). "Recently, it was described in EGFR-mutated lung cancer cells that the up-regulation of CBL proto-oncogene c (CBLC) contributes to tumor progression due to dysregulation of activated EGFR." (PMID 34487971, 2021). "Other genes from this pathway that we found differentially expressed in our experiments are CBLC that was reported as associated with lung cancer progression and CRKL which promotes tumorigenesis, cancer cell survival, and gefitinib therapy resistance in non-small cell lung cancer." (PMID 35290621, 2022). "In the TCGA cohort, the AUC values ​​of CBLC, FABP4, GDF10, and LTBP4 genes were 0.982, 0.997, 0.980, and 0.983, respectively, indicating that these genes have a high diagnostic efficiency in distinguishing lung cancer samples from normal control groups." (PMID 40766337, 2025). "CBLC could delay the accumulation and activation of AURKA through consumption to prevent cancer cells from entering cell division and increase the apoptosis of lung cancer cells." (PMID 36339610, 2022).
Breast tumor (4 papers, 2015 to 2023). "Breast tumor formation is increased by CBLC overexpression, which suppresses TGF-β (transforming growth factor beta)." (PMID 37900178, 2023).
Hydrocephalus (4 papers, 2017 to 2024). Hydrocephalus is an active distension of the ventricular system of the brain resulting from inadequate passage of CSF from its point of production within the cerebral ventricles to its point of absorption into the systemic circulation. "Previously, c.567dupT has been detected in early-onset patients with hydrocephalus secondary to cblC deficiency." (PMID 36056359, 2022). "Some researchers have also considered that screening for inherited metabolic diseases should be immediately conducted when pediatric patients with cblC defects develop progressive and refractory hydrocephalus." (PMID 36590295, 2022). "NBS for the cblC defect should be considered since survival and prevention of severe complications such as HUS, hydrocephalus and haematological abnormalities in early-onset patients can be improved by early treatment." (PMID 27905001, 2017).
cblC (3 papers, 2018 to 2025). "Here, we report a new cause of the cblC class of inborn errors of vitamin B12 metabolism that we name “epi-cblC”." (PMID 29302025, 2018). "Here, we identify a cause of the autosomal recessive cblC class of inborn errors of vitamin B12 metabolism that we name “epi-cblC”." (PMID 29302025, 2018).
hemolysis (3 papers, 2017 to 2024). Disruption of the integrity of the erythrocyte membrane causing release of hemoglobin. "Therefore, it is proposed that screening for cblC deficiency be considered in patients presenting with either ambiguous intravascular hemolysis, hematuria, and proteinuria, or renal thrombotic microangiopathy (TMA)." (PMID 38977946, 2024). "Therefore, cblC deficiency was suggested to be screened in patients with either unclear intravascular hemolysis, hematuria, and proteinuria or renal TMA." (PMID 36704130, 2022).
melanoma (3 papers, 2018 to 2021). A malignant, usually aggressive tumor composed of atypical, neoplastic melanocytes. "Although PRDX1 gene variants have not been identified in human tumours, it is known that a tumorigenic human melanoma cell line, named MeWo-LC1, has a cellular phenotype identical to that of cblC patients’ cells." (PMID 34215320, 2021).